CD40 (CD40 molecule)
Diseases named in the same sentence as CD40 in open-access papers (continued):
Sharing a sentence is not in itself a finding about the gene and the disease.
tumor (continued). "A recent report demonstrates the ability of a CD40 agonist to induce tumor regression of pancreatic adenocarcinoma in both a pre-clinical trial and a human clinical trial." (PMID 23898464, 2013). "In principal, CD40 signaling will only be initiated upon tumor specific binding of the bi-specific antibody fragment thus ensuring a restricted CD40 co-stimulatory signaling." (PMID 23840967, 2013). "Recently, we reported two other fusion proteins, CTLA-4•FasL and CD40•FasL, with cytotoxic activity against tumor cells." (PMID 24130833, 2013). "CD40 activation can reverse immune suppression and drive anti-tumor T cell responses by mediating the “licensing” of antigen-presenting cells." (PMID 24303367, 2013). "The use of agonistic anti-CD40 antibodies as a single intervention has been successful at activating tumor DCs to stimulate T cell rejection of a murine tumor model." (PMID 24339824, 2013). "Combined treatment of anti-CTLA4, PD-1, TIM-3 and CD40 mAbs also suppressed tumor growth but was less efficacious with mean survival time 49 days." (PMID 24367702, 2013). "Our goal was to improve upon cancer vaccination with tumor antigens by delivering PSMA via a CD40-targeted adenovirus vector directly to DCs as an efficient means for activation and antigen presentation to T-cells." (PMID 23056548, 2012). "Binding enhances MHCII expression as well as dendritic cell activity and is therapeutically effective against several CD40 + human tumours." (PMID 23125850, 2012). "Administering DCs infected ex vivo with CD40-targeted Ad5-huPSMA, as well as direct intraperitoneal injection of the vector, resulted in high levels of tumor-specific CTL responses against RM-1-PSMA cells pretreated with Ad5-IFNγ as target cells." (PMID 23056548, 2012). "This tumor growth was significantly delayed compared with the animals immunized with the CD40-targeted Ad5-huPSMA but challenged with parental RM-1 cells (that do not express the human PSMA antigen)." (PMID 23056548, 2012). "In a mouse model of metastatic renal cancer, the use of anti-CD40 agonist mAb in combination with IL-2 or IL-15 can mediate tumor regression by inducing an inflammatory milieu that inhibited intratumoral Treg and MDSC activities." (PMID 22778760, 2012). "Among these antibodies, agonist anti-CD40 Abs have been extensively studied and exhibited clinical activities in a range of tumor types." (PMID 22778760, 2012). "In vitro CD40-activation with IFNγ was required to effectively reprogram tumor-induced M2-like macrophages into activated IL-12 producing M1 cells." (PMID 22176642, 2011). "CD40 therapy resulted in the stimulation of secondary lymph node resident macrophages to migrate into the tumor tissue." (PMID 22176642, 2011). "The CD40 pathway plays an important role in anti-tumor responses by promoting cytotoxic lymphocyte (CTL) responses and the differentiation of helper T cells into cells with the Th1 phenotype." (PMID 21912605, 2011). "Data presented here confirm our previous findings that cell hybrids of human MSI+ tumor cells and CD40 Bs as APC can easily be generated." (PMID 21943054, 2011). "In the present study, we have evaluated the potency of T cell induction by semiallogenic cell fusions of a MSI+ tumor cell line and CD40 Bs." (PMID 21943054, 2011). "We chose microsatellite instability-induced frameshift antigens as ideal to test for induction of tumor specific T cell responses by semiallogenic fusions of microsatellite instable carcinoma cells with CD40-activated B cells." (PMID 21943054, 2011). "We suggest that semiallogenic cell hybrids of human MSI+ tumor cells and CD40 Bs are a feasible approach to generate polyepitope vaccines with the capacity to induce polyvalent immune responses." (PMID 21943054, 2011). "The CD40 pathway has been recognized as a major component of the anti-tumor response and holds promise as a novel target for therapies for advanced human malignancies." (PMID 21912605, 2011).
tumor (continued). "A remarkable anti-tumor effect of re-directed macrophages has been recently reported in human pancreatic cancer with the use of agonist anti-CD40 mAb." (PMID 24213109, 2011). "Local and systemic administration of activating anti-CD40 antibody either alone or in conjunction with other therapies has been shown to alter the phenotype of DC subsets and augment tumor specific CD8+ T-cell responses in vivo." (PMID 20976125, 2010). "Tumours which express CD40 can stimulate the generation of anti-tumour effector cells and CD40 activation in vivo enhances the survival of activated T cells and promotes DC accumulation and survival." (PMID 21103345, 2010). "Treatment of tumour-bearing mice with activating anti-CD40 antibody following gemcitabine chemotherapy induced long-term cures in >80% of mice bearing malignant mesothelioma's (MM)." (PMID 20976125, 2010). "On this basis, engagement of CD40 on DC to induce anti-tumour immune responses is a prolific area of research and both recombinant soluble CD40 ligand and CD40 agonist antibodies have entered clinical trials." (PMID 20211016, 2010). "Recent studies have suggested that CD40 ligation can enhance cytotoxic T lymphocytes activity and reduce tumor growth." (PMID 19865524, 2009). "CD40 activation of APC plays an important role in driving anti-tumor T cell-mediated immune responses, and agonist CD40 antibodies which mimic the action of CD40 ligand are thought to represent promising therapeutics for novel immune strategies for cancer." (PMID 19906293, 2009). "Among the many microenvironmental factors now appreciated to contribute to APC licensing, ligation of the cell surface molecule CD40 on the surface of both DC and B cells is fundamental, particularly for tumor immunity." (PMID 19906293, 2009). "The humanised monoclonal antibody targeting CD40 (SGN-40) induces potent antitumour effects when tested on CD40-positive tumour cell lines representing a variety of haematologic malignancies." (PMID 19066610, 2009). "In tumor-bearing mice, agonist CD40 antibodies overcome T cell tolerance, evoke effective cytotoxic T cell responses, and enhance efficacy of anti-tumor vaccines." (PMID 19906293, 2009). "When the proliferation of activated B cells and the transformed B cells were compared in vitro, the tumor cells were approximately 10-fold more sensitive to L-744,832 treatment than naïve B lymphocytes stimulated with antigen receptor and CD40 antibodies." (PMID 18489761, 2008). "C4BP and CD40 co-localised to ductular structures within the tumour as well as surrounding tumour cells." (PMID 17225862, 2007). "In selected samples of tumour tissue we carried out dual immunofluorescence to look for cellular co-localisation of CD40 and C4BP." (PMID 17225862, 2007). "In this respect, we have recently shown that incubation of CD40-positive NB cells with soluble or insoluble CD40L leads to tumour cell apoptosis." (PMID 15150552, 2004). "On the other hand, BAX expression was associated with expression of CD40 and CD40L, suggesting that all three are linked in their behaviours in this tumour type." (PMID 12592374, 2003). "Previous studies have shown that ligation of CD40 on the surface of tumour cells by CD40L can induce inhibition of cell proliferation and apoptosis." (PMID 12771917, 2003). "The most important finding of this study is the constitutive expression of CD40 mRNA and protein in all of the tumour samples tested." (PMID 12771917, 2003). "The overall increase in apoptotic rates was moderate and remained lower in tumour samples than in control CD40-activated normal tonsil B cells." (PMID 9683298, 1998). "Novel inhibitory and co-stimulatory immune checkpoints such as lymphocyte activation gene-3 (LAG-3), T cell immunoglobulin mucin-3 (TIM-3), T cell immunoreceptor with Ig and ITIM domains (TIGIT), OX40, CD137 (4-1BB), and CD40 are examined for their potential to enhance anti-tumor immunity." (PMID 41832248, 2026).
tumor (continued). "Bioinformatically, high A3C expression was associated with an activated anti-tumor immune microenvironment, characterized by enhanced CD8+ T cell infiltration, reduced M2 macrophage abundance, and upregulation of the immune checkpoint CD40." (PMID 41514678, 2026). "Single-cell analysis identified a distinct population of inflammatory monocytes that were enriched for an IFNγ response signature in CD40 agonist-treated tumors, suggesting that these cells may be important for tumor control." (PMID 41676732, 2026). "CD40, which is taken over by tumour cells, further facilitates invasion in chemoresistant GBM." (PMID 41179304, 2025). "The rationale behind this combination is that chemotherapy can reduce tumor load and potentially expose more tumor antigens, while CD40 agonists may strengthen the immune system’s ability to detect and target these antigens." (PMID 40003965, 2025). "Moreover, the lack of cross-presenting DCs and the prevention of DC recruitment into the tumor abolish the Delta-24-RGD+anti-CD40 anti-DMG effect." (PMID 40578365, 2025). "Additionally, the concurrent administration of TNF and anti-CD40 mAb boosts neutrophil activation and toxicity, further promoting tumor cell apoptosis and clearance by enhancing oxidative damage and N1 neutrophil recruitment in the TME." (PMID 39925807, 2025). "Recent studies suggested that targeting TAMs’ phenotypic reprogramming, using agents like CSF-1R inhibitors or CD40 agonists, can boost their antigen-presenting efficiency and activate anti-tumor T-cell responses, offering a novel strategy for HCC immunotherapy." (PMID 41361104, 2025). "Changes in CD40 and CD166 membrane levels were found to be associated with their respective expression data, confirming that IFITM1 plays a significant role in regulating genes associated with tumor progression." (PMID 40314078, 2025). "This, in the presence of a CD40 agonist, may explain why DCs have an improved ability to uptake tumor antigens compared to other APCs in DMG-bearing mice." (PMID 40578365, 2025). "Whether repeated administrations of anti-CD40 could improve the long-term anti-tumor effect must be further studied." (PMID 40578365, 2025). "Collectively, these biological effects induced by mitazalimab align with the hypothesized mechanism of anti-tumor activity for a CD40 agonist when combined with chemotherapy and support the treatment approach implemented in the OPTIMIZE-1 trial." (PMID 41061701, 2025). "CD40 is expressed on the surface of B cells, monocytes, macrophages and dendritic cells (DCs) and plays a key role in bridging innate and adaptive immunity by “licensing” DCs to prime and activate T cells, thereby triggering tumor-specific T cell immunity." (PMID 41061701, 2025). "In one of the works, they have demonstrated that tumor regression may result from naïve B-cells enriched with tumor-derived autophagosomes that selectively capture TSAs after being triggered by CD40 or TLR in E.G7 murine thymoma models." (PMID 40733666, 2025). "TAMs activated by CD40 show enhanced antigen presentation and T cell costimulation, associated with increased MHC class II and CD86 expression, and have been shown to promote tumour regression in a murine model of PDAC." (PMID 40385641, 2025). "However, it had a limited effect on the proportion of DCs in tumour tissue, in contrast to CD40 mAb‐H‐mIgG1, which markedly decreased DCs." (PMID 40726342, 2025). "Additionally, CD166, CD146 and CD40 play crucial roles in activating immune responses in tumor tissues." (PMID 40314078, 2025). "CD40 agonism can also reprogramme TAMs and stimulate the development of anti-tumour myeloid cells." (PMID 40385641, 2025). "Indeed, the percentage of mCherry+ tumor macrophages increased with the anti-CD40 alone as compared to the Delta-24-RGD virus and the combination." (PMID 40578365, 2025).
tumor (continued). "Similarly, in a RCC model undergoing IL-2/anti-CD40 immunotherapy, macrophage-dependent NO in the tumor microenvironment was essential to regulate the activity of MMPs and the expression of adhesion molecules, which was the basis for metastasis." (PMID 40083710, 2025). "Moreover, following treatment with the combination of SUP3 and Flt3L, CD103 + cDC1s within the tumor continued to exhibit high expression of co-stimulatory molecules, such as CD40, CD80, and CD86 expression." (PMID 41291775, 2025). "In addition, the TLR ligands and anti-CD40 antibody in the rWTC-MBTA are used as adjuvants to amplify the tumor-specific immune response." (PMID 39941108, 2025). "Next, we monitored tumor growth in MC38-bearing mice that were repeatedly treated with anti-CD40." (PMID 41176316, 2025). "The expression of CD40L on tumor cells could diminish the effectiveness of CD40-targeted treatments or even promote tumor advancement." (PMID 40003965, 2025). "This was aimed to determine whether a strong contrast of CD40 expression has an impact on the tumor progression in WT and CD8+ T cell–specific CD40L−/− mice." (PMID 40397730, 2025). "After administration of anti-CD40 antibodies, which enforces pro-inflammatory macrophage reprogramming, 29 30 monocyte-derived macrophages expressing pro-inflammatory, antigen-presentation genes accumulate at the tumor margins." (PMID 41176316, 2025). "CD40, a familiar immune checkpoint, is abundantly expressed on antigen-presenting cells, macrophages, and even tumor cells, where it interacts with helper T cells and mediates the enhancement of anti-tumor T cell responses." (PMID 40108724, 2025). "Moreover, the use of TLR agonists, STING agonists, and antibodies targeting CD40 can further promote dendritic cell activation and function, thereby strengthening the body’s anti-tumor immunity." (PMID 40297580, 2025). "Moreover, tumor-supportive neutrophil subpopulations can recruit Tregs through CD40 signaling, thereby enhancing immune tolerance within the TME." (PMID 40050933, 2025). "Despite the ability of the combination therapy of PD-1 blockade and CD40 agonist to enhance Th1 cell presence in “cold” regions, the overall T cell activity remained suboptimal compared to “hot” regions, resulting in an inability to induce tumor rejection." (PMID 40739089, 2025). "Furthermore, CD40 is expressed on normal APCs and B cells, raising concerns about off-tumor activation and systemic immune-related toxicities." (PMID 40597436, 2025). "The priming dose of mitazalimab in OPTIMIZE-1 was specifically designed to leverage CD40-mediated degradation of tumor stroma before the initiation of chemotherapy, which may enhance drug delivery and efficacy." (PMID 41061701, 2025). "The therapeutic synergy between fungal β-glucans and CD40 agonism demonstrates that components of the mycobiota, or their molecular analogs, can be leveraged to overcome tumor-induced immunosuppression, particularly in settings where conventional checkpoint inhibition fails." (PMID 41163402, 2025). "Therefore, it appears that the triple combination triggers a state in which viable tumor cells persist but are controlled by a mechanism enhanced by CD40 agonism." (PMID 40299790, 2025). "Second, the use of bulk RNA sequencing precluded determining whether tumor or immune cells are the principal contributors to CD40-related signaling." (PMID 41182434, 2025). "Additionally, MYCN-A tumors exhibited the downregulation of immune-activating genes such as CD48 and CD86, and a slight decrease in CD40 expression, potentially contributing to an immunosuppressive tumor microenvironment." (PMID 39860532, 2025). "Moreover, neutrophil activation (e.g., via TNF, a CD40 agonist, or tumor-targeting antibodies) induced tumor eradication through oxidative damage." (PMID 40563651, 2025).
tumor (continued). "To investigate the association between high expression of CD40 and the T-cell costimulatory molecules CD28 or GITR in an "immunologically hot" tumor microenvironment, we performed a univariable analysis stratified by the tumor's CD4/CD8 expression status." (PMID 41182434, 2025). "This “site-dependent immune escape” could be reversed with CD40 agonists, restoring T cell priming and expanding the repertoire of tumor-reactive clones through epitope spreading." (PMID 40475782, 2025). "The MyD88/CD40 signaling modules, whether inducible or constitutive, significantly improve the survival, persistence, and anti-tumor activity of CAR T-cells by driving the activation of NF-κB and MAPK." (PMID 39941106, 2025). "These discrepancies may be due to differences in the timing and sequence of CD40 agonist administration with respect to chemotherapy and their impact in shaping anti-tumor immune responses." (PMID 41061701, 2025). "In PDAC, CD4+ T cells were found to promote differentiation of monocytes into MHC class II anti-tumor TAMs through cognate antigen recognition and downstream CD40 and IFN-γ pathways; in turn, these MHC class II TAMs are critical promoters of anti-tumor Th1 cells and anti-tumor immunity." (PMID 40453088, 2025). "Smart RT biomaterials, such as LIFE Biomaterial, are made of a biodegradable and biocompatible mixture of natural polymers that undergo gelation within the tumor microenvironment, allowing for a sustained local release of the anti-mouse CD40 monoclonal antibody." (PMID 41155910, 2025). "Approaches that target tumor-associated macrophages, such as CSF1R inhibition, CD40 agonists, or TLR/STING agonists, may promote M1 polarization and strengthen innate antitumor activity." (PMID 41374320, 2025). "Using spatial transcriptomics and single cell sequencing of MC38 tumor cells in mice treated with agonist anti-CD40 antibody therapy, it was demonstrated that heme-driven NRF2 activation in macrophages drives metabolic reprogramming towards immunosuppressive tumor associated macrophages (TAMs)." (PMID 40946102, 2025). "In addition, CD40-targeted therapies have been used to reprogram macrophages, as anti-CD40 therapy not only promotes tumor cell death but also contributes to matrix degradation, highlighting its potential for modifying the TME." (PMID 40420798, 2025). "We have previously demonstrated these in vivo activated B cells express CD19, B220, CD23, HEL+ with subtle upregulation of MHC-II and CD95.4,5 Importantly, no proliferation is observed when naïve 5C.C7 CD4 T cells are transferred into I-E- anti-CD40 activated SWHEL transgenic tumour bearing mice." (PMID 38125720, 2024). "In addition, impaired cDC1 function by deletion of either MHC class II or CD40 prevented rejection in a tumor-OVA model with immunization based on soluble antigen." (PMID 39559560, 2024). "However, it is important to note that the roles of CD40L can vary depending on the specific type, location, and expression levels of CD40L and CD40 within different tumor tissues." (PMID 39120299, 2024). "Ceralasertib treatment caused increase in the percentage of tumor CD11c+MHC II+ dendritic cells (DCs) and marked up-regulation of the expression of molecules associated with DC activation: MHC class II (IAb), MHC class I (H2Kb), CD40, and CD80." (PMID 38402224, 2024). "In contrast, Nano/CD40 exhibited moderate anti-tumor efficacy." (PMID 38468289, 2024). "CD40 was found to play a crucial role in tumor growth and signaling pathways." (PMID 39682256, 2024). "Our ability to use preclinical models that recapitulate the human expression of CD40 and FcγRs has allowed us to prioritize the most biological rational approaches and which tumor types to focus on in future studies with 2141-V11, either alone or in combination with standard or novel therapies." (PMID 38883779, 2024).